TRIM5 (tripartite motif containing 5)
Diseases named in the same sentence as TRIM5 in open-access papers (continued):
Sharing a sentence is not in itself a finding about the gene and the disease.
infection (continued). "More importantly, the effects of class I Mhc on SIVmac239 replication do not manifest during the acute stage of infection, whereas the correlation with TRIM5 genotype is already apparent during acute infection." (PMID 20808775, 2010). "Under such conditions, it is possible that the effect of TRIM5 genotype on infection will be even more pronounced." (PMID 20808775, 2010). "Cellular CypA binds to the capsid proteins of several lentiviruses, and we believe that TRIM5-CypA proteins were at one time selected for the ability to block infection by retroviral pathogens, possibly related to modern lentiviruses." (PMID 18389077, 2008). "This provides new data on the role of host factors in the replication of SVA and indicates that targeting TRIM5 may help to develop new agents to counter infection and replication of the virus." (PMID 39143491, 2024). "Most recently, TRIM5 was reported to restrict the infection and replication of poxvirus." (PMID 39143491, 2024). "Interestingly, N74D CA-NC complexes bound to C-terminal POM121 as efficiently as WT CA-NC complexes, which is consistent with the infection block observed using TRIM5 fusion proteins." (PMID 37355754, 2023). "Thus, T-cell receptor-driven signalling and cytokine secretion dominate in vitro T-cell infection experiments, obviating virus-induced changes including cGAS/TRIM5 activation." (PMID 36289397, 2022). "To do this, we devised a scheme of sequential infections in which THP-1 macrophages are “primed” with human TRIM5-restricted single-cycle viruses prior to being “challenged” by GFP-expressing HIV-1 pseudovirions with wild type (TRIM5-resistant) capsid." (PMID 33052966, 2020). "We next asked whether this effect was sufficient to affect the outcome of infection with TRIM5-resistant viruses." (PMID 33052966, 2020). "Finally, by knocking down TRIM5 prior to infection, we confirmed that endogenous TRIM5 protein in the P. alecto cells did not contribute to the restriction of HIV-1." (PMID 32934084, 2020). "We found that the signaling induced by HIV-1 CA P90A infection could potently inhibit the ability of otherwise TRIM5-resistant HIV-1 and Sendai virus to infect THP-1 macrophages." (PMID 33052966, 2020). "Finally, infection of primary human-monocyte-derived dendritic cells (DCs) resulted in upregulation of TRIM5 expression." (PMID 31189110, 2019). "In summary, the finding that primate TRIM5α can recognize and degrade NS2B/3 from specific flaviviruses combined with a strong antiviral role in the type I IFN response suggests that TRIM5 has a high potential to function as an important human barrier to infection with emerging flaviviruses." (PMID 31189110, 2019). "Thus, TRIM5 and APOBEC3 are more potent in restricting heterologous infection than infection caused by the lentivirus of the corresponding particular species." (PMID 23917352, 2013). "For these macaques, the restrictive alleles did not prevent infection but the virus maintained a low level of replication until the appearance of mutations associated with TRIM5 resistance." (PMID 23990789, 2013). "Retroviral capsid recognition by Trim5 blocks productive infection." (PMID 23675300, 2013). "Animals with the restrictive TRIM5 genotypes were nearly all protected from acquisition by the vaccine, but those with permissive TRIM5 genotypes also had significantly lower infection rates than the corresponding controls, which had a particularly high rate of infection." (PMID 23025660, 2012). "As expected, infants who required a greater number of challenges before infection showed no bias toward protective TRIM5 alleles, and conversely, infants who became infected after fewer challenges were not more likely to express alleles associated with greater susceptibility to infection." (PMID 29359183, 2018).
infection (continued). "Rhesus macaques co-dominantly express two TRIM5 alleles and can therefore be grouped as most resistant (TRIM5TFP/TRIM5TFP, TRIM5TFP/TRIM5CypA, and TRIM5CypA/TRIM5CypA), moderately resistant (TRIM5TFP/TRIM5Q and TRIM5CypA/TRIM5Q), or susceptible (TRIM5Q/TRIM5Q) to SIVsmE660 infection." (PMID 24651676, 2014). "The qRT-PCR results showed that the mRNA expression of TRIM5 in 3D4/21 cells infected with SVA was significantly greater than that in control cells at 12 and 24 h post-infection (hpi) (P < 0.01)." (PMID 39143491, 2024). "TVs expressing sgRNAs targeting known RFs like TRIM5, IFI16, IFITM2, SAMHD1, GBP5 and IFITM1 were enriched after 15 and 20 days post-infection confirming that targeting RFs provides a selection advantage to the respective viruses." (PMID 38714682, 2024). "TRIM5 can bind to HIV-1 viral capsid proteins, leading to uncoating and exposure of the nucleoprotein complex, thus inhibiting the first stages of infection." (PMID 37685953, 2023). "This is also evidenced by modest rescue of single-round infection (GFP expression) of HIV-2 and HIV-1(O) when TRIM5 is depleted in macrophages." (PMID 36289397, 2022). "Several other antiviral proteins, including RIG-I, MDA5, OAS, RNase L, Trim5, ADAR1, ZAP, cGAS and RNA helicases, can be recruited to SGs during infection, suggesting that these are antiviral SGs (avSGs) with a role in antiviral signalling." (PMID 35098996, 2022). "Whereas TRIM5 molecules containing bovine SPRY (blue and red) suppressed infection by SIVmac and FIV, those carrying human SPRY domain (green and purple) minimally blocked these viruses." (PMID 36258028, 2022). "These TRIM5-capsid interactions show a high degree of both host and viral species specificity, with human TRIM5 historically being considered unable to bind and restrict HIV-1 despite its ability to efficiently block infection by other retroviruses." (PMID 33052966, 2020). "We identified TRIM34, a TRIM5 paralog, as an HIV-1 restriction factor capable of inhibiting infection by an HIV-1 N74D capsid mutant virus as well as several lentiviruses from monkeys." (PMID 32282853, 2020). "Infection of these TRIM34-overexpressing, TRIM5-KO THP-1 pools demonstrates that the restriction of viral replication measured for the HIV-1 N74D capsid mutant is lost when TRIM5α is missing." (PMID 32282853, 2020). "The expression of rhTRIM5α restricted infection of vesicular stomatitis virus glycoprotein (VSV-G) pseudotyped HIV-1 in 293 cells, demonstrating that these cells are appropriate to observe TRIM5-mediated restriction." (PMID 31189110, 2019). "A CypA fusion with TRIM5 (a member of the tripartite motif family) that is unique to New World owl monkeys also targets HIV-1 CA, but this interaction potently inhibits infection." (PMID 18565229, 2008). "To explore this hypothesis, we performed infection assays in CD4+ T cells using free viral particles and evaluated the transcriptional expression of the viral restriction factors SAMHD1, TRIM5, and APOBEC3G." (PMID 35802715, 2022). "Finally, we found that HIV-1(M) CA Q50Y + R120 behaved like non-pandemic viruses HIV-1(O) and HIV-2, becoming more sensitive to human TRIM5 restriction than WT HIV-1(M), as evidenced by rescue of infection by TRIM5 depletion in U87 cells." (PMID 36289397, 2022). "In this work, we established that PTM TRIM5 does not block infection of KFDV, further providing rationale to characterize the PTM model for KFDV pathogenesis." (PMID 34855915, 2021). "The truncated feline TRIM5 appears to be without any antiretroviral activity as overexpression of the feline TRIM5 does not prevent infection with murine leukemia virus, HIV-1 or a simian immunodeficiency virus (SIV) of macaques (SIVmac)." (PMID 22069525, 2011). "Surprisingly, transmission occurred even in individuals bearing restrictive TRIM5 genotypes, resulting in attenuation of replication rather than an outright block to infection." (PMID 20808775, 2010).
infection (continued). "To further investigate how SIVsmm overcame TRIM5 restriction in these animals, we isolated SIV RNA from plasma samples sequentially collected from Rh444, Rh447, Rh458 and Rh063 at different time points during the course of infection, cloned and sequenced the full gag coding regions." (PMID 23990789, 2013). "Alternatively, there are published reports indicating that TRIM5 gene expression is interferon-regulated; thus, it is also possible that the full impact of TRIM5 on viral replication in vivo is not manifest until after the first round of infection is well underway." (PMID 20808775, 2010). "Thus the low HIV-2 reservoirs differ from HIV-1 reservoirs by the lack of monocytic infection and a limited infection of TCM associated to a lower expression of a potential alternative HIV-2 co-receptor, CXCR6 and a higher expression of a restriction factor, TRIM5." (PMID 31095640, 2019). "However, unlike owl monkey TRIMCyp, macaque TRIM5-CypA did not block infection by HIV-1." (PMID 18389077, 2008). "In these experiments, TRIM5 knockout THP-1 cells expressed reduced IFNB1 under basal conditions and IFNB1 expression was not increased in response to HIV-1 CA P90A infection." (PMID 33052966, 2020). "However, feline TRIM5 is not functional because of the insertion of premature stop codon, and feline tetherin is unable to restrict spreading FIV infection." (PMID 29636069, 2018). "We infected TRIM5 knockout and control Jurkat and THP-1 cells with TRIM5α-sensitive vectors (NRC10, EC8, EC5-2) that were treated or not with AT-2, and could not detect any productive infection upon inactivation of the vectors with AT-2, as expected." (PMID 30419009, 2018). "Indeed, both IFN receptor blockade and TRIM5 depletion rescued infection of non-pandemic viruses in MDM and suppressed macrophage activation of inflammatory gene expression, suggesting important roles for both signalling and physical caging of incoming capsids by TRIM5, for antiviral activity." (PMID 36289397, 2022).
tumor (7 papers, 2009 to 2025). "The correlation analyses between the 8 TRIM molecules and TMB (tumor mutational burden)/MSI (microsatellite instability)/ICMs discovered that as the expression level of TRIM5/21/22/24/28/34/47 increased, the TMB score also increased significantly, while TRIM17 showed an opposite outcome." (PMID 37367937, 2023). "Based on this approach, we found two genes (Trim5 and Tlr1) correlated with the increased tumor phenotype of the GM:F344 group." (PMID 37458451, 2023). "Some genes (TRIM22/TRIM38/TRIM5/TRIM59) are expressed lower in tumor cells than in other cell types." (PMID 35928444, 2022). "Several genes are contained within this interval that might be involved in brain development and/or tumor suppression, including TRIM3 and a cluster of genes encoding the more distantly related TRIM5, TRIM6, TRIM22, and TRIM34 genes." (PMID 19250537, 2009). "Several genes associated with the GO category of “Regulation of viral entry into host cells,” TRIM5, TRIM21, TRIM22, and TRIM38 were over-expressed in GBM compared to ODG and non-tumor samples." (PMID 35896929, 2023).
cancer (4 papers, 2022 to 2023). A tumor composed of atypical neoplastic, often pleomorphic cells that invade other tissues. "Like the TRIM5 proteins, toll-like receptors (TLRs) activate the adaptive immune response in cancers." (PMID 37458451, 2023). "Expression analysis, using UALCAN on these genes in cancer vs. normal tissues, resulted in 9 differentially expressed TRIM genes (TRIM5/6/7/15/21/26/39/41/68) (P <0.001)." (PMID 35617983, 2022).
TRIM5 also shares sentences with these, for which no sentence is quoted: rubella (3 papers); autoimmune disease (2); Autoimmunity (1); cardiovascular diseases (1); cerebral malaria (1); coinfection (1); COVID-19 (1); dengue (1); Hepatitis (1); hepatitis B (1); influenza (1); lentivirus infection (1); liver disease (1); liver steatosis (1); pharyngeal cancers (1); respiratory diseases (1); viral diseases (1).